BRCA1 (BRCA1 DNA repair associated)
Diseases named in the same sentence as BRCA1 in open-access papers (continued):
Sharing a sentence is not in itself a finding about the gene and the disease.
breast cancer (continued). "This combined approach not only improves the sensitivity and specificity of breast cancer detection but also facilitates earlier detection of breast cancer in BRCA1/2 mutation carriers." (PMID 39421188, 2024). "In another study including 223 breast cancer patients with BRCA1 mutation, CBC incidence was higher in the BRCA1 mutation group compared to sporadic breast cancer patients." (PMID 38689097, 2024). "Conversely, studies observed that BRCA1 negatively regulates autophagy in MCF-7 breast cancer cells, with BRCA1-loss increasing autophagic vacuoles and ROS levels." (PMID 39199310, 2024). "This approach allows us to move beyond the traditional focus on BRCA1/2 genes and explore the contribution of other high- and moderate-risk genes to breast cancer susceptibility in this specific population." (PMID 39590369, 2024). "Previous studies in this population have identified significant founder mutations, including the BRCA1 c.4964_4982del variant, highlighting the importance of population-specific genetic analyses in hereditary breast cancer risk assessment." (PMID 39590369, 2024). "Breast cancer patients with BRCA1/2 germline mutation carry increased risk of contralateral breast cancer (CBC) development." (PMID 38254240, 2024). "Initial studies have shown that individuals with BRCA1 or BRCA2 mutations were 84% more susceptible to breast cancer and 40% more susceptible to ovarian cancer throughout their lifetime 30-32." (PMID 38706918, 2024). "In a similar vein, constitutive BRCA1 methylation is a substantial risk factor for serous ovarian cancer and is associated with a 3.5-fold increased risk of early-onset breast cancer." (PMID 38542081, 2024). "Olaparib, the first poly(ADP-ribose) polymerase (PARP) inhibitor to be developed, is effective in treating women with breast cancer who have germline pathogenic variants in BRCA1 and/or BRCA2 (gBRCAm), both in the metastatic and the adjuvant setting." (PMID 38588696, 2024). "At the monogenic level, inherited mutations in BRCA1/2, the susceptible tumour suppressor genes for breast cancer (BC), among other cancers, have long been contemplated as the main genetic constituents in BC." (PMID 39791706, 2024). "Ipsilateral breast cancer event risk is also reported to be higher for BRCA1/2 variant carriers compared with the general population of patients treated with BCT for breast cancer." (PMID 38916888, 2024). "Further, expressional studies are required to confirm BRCA1 gene dysregulation in breast cancer due to these variants." (PMID 38952531, 2024). "Clinically, PARP inhibitors have improved outcomes compared with conventional therapy for both advanced and early-stage BRCA1/2-mutated breast cancer as well as ovarian and prostate cancers by extending disease-free and overall survival." (PMID 39730675, 2024). "Recently in breast cancer, some naturally occurring alternative transcripts of BRCA1 and BRCA2, through mutational variants in the splicing sites, have been found to encode protein isoforms with residual tumor suppressive activity." (PMID 39493168, 2024). "Activating mutations of oncogenes such as C-MYC found in BRCA1/2 PV breast cancers further blunt the immune response in the tumour microenvironment." (PMID 39682099, 2024). "Overall, the present study revealed that FCR is highly prevalent in women with breast cancer who carry a BRCA1/2 mutation." (PMID 39192282, 2024). "Overall, FCR was found to be a significant issue in breast cancer survivors carrying a BRCA1/2 mutation, even though most participants (84.2%) had undergone at least one type of prophylactic surgery." (PMID 38192174, 2024).
breast cancer (continued). "The discovery of synthetic lethality between PARP enzymatic inhibition and BRCA1/2 mutations ultimately led to the rapid clinical translation of PARP inhibitors (PARPi) for the treatment of BRCA1/2-mutant breast cancers." (PMID 38956205, 2024). "Upregulated expression of BRCA1 and BRCA2 genes was reported in BC and ovarian cancer, furthermore, high BRCA1 gene expression was demonstrated to increase the risk of early distant metastasis in ER + breast cancer patients." (PMID 38165507, 2024). "Before the Korean NIC expansion, 32.8% of new patients who underwent primary breast cancer surgery were tested for the BRCA1/2 mutation." (PMID 38791944, 2024). "Ten percent of patients with breast cancer, and probably somewhat more in patients with ovarian cancer, have inherited germline DNA mutations in the breast and ovarian cancer genes BRCA1 and BRCA2." (PMID 38540206, 2024). "The study found that among the BRCA1 mutation carriers, a risk-reducing mastectomy was associated with a 90% reduction in the risk of developing subsequent breast cancer (incidental cancer) during a median follow-up of 3.6 years." (PMID 38791944, 2024). "The DNA repair protein PARP-1 emerged as a valuable target in the treatment of tumor entities with deficiencies of BRCA1/2, such as breast cancer." (PMID 39456536, 2024). "This biosensor demonstrated high sensitivity for detecting BRCA1 gene mutations, offering a significant improvement in early breast cancer diagnostics and potentially allowing for earlier intervention and treatment." (PMID 38730959, 2024). "Most importantly, HRD testing expands the potential populations beyond breast cancer with BRCA1/2 mutation." (PMID 39334297, 2024). "Ten BRCA1/2 mutation carriers developed breast cancer, one developed ovarian cancer, and three developed other cancers." (PMID 39590130, 2024). "Germline BRCA1/2 pathogenic or likely pathogenic variants (gBRCAm) are clinically relevant for treatment selection in breast cancer because they confer sensitivity to poly(ADP-ribose) polymerase (PARP) inhibitors." (PMID 39237557, 2024). "The proportion of breast cancers in the general population attributed to BRCA1 and BRCA2 germline pathogenic variants is approximately 5–10%, but this proportion is much higher (up to 55%) in selected families referred to familial cancer clinics." (PMID 39402389, 2024). "Here, by studying resistance to poly(ADP-ribose) polymerase (PARP) inhibitors in BRCA1/2-deficient mammary tumours, we identify a function for γH2AX in orchestrating drug-induced replication fork degradation." (PMID 38789420, 2024). "The subsequent randomized phase 3 EMBRACA trial in patients with BRCA1/2-mutated advanced breast cancer showed an improvement compared to standard therapy in progression-free survival (PFS) (8.6 vs. 5.6 months)." (PMID 38010394, 2024). "Concerning blood folate levels, high plasma levels of B9 have been associated with an increased risk of breast cancer in women with BRCA1 and BRCA2 mutations." (PMID 39125744, 2024). "The detection of BRCA1 gene mutations, which are associated with increased breast cancer risk, has been a focus of SPE-based genetic biomarker sensing." (PMID 39275589, 2024). "The epidemiology of breast cancers arising in the context of a BRCA1 or BRCA2 mutation is different than that of sporadic cancers." (PMID 39060255, 2024). "The treatment of tumors with BRCA1/2 mutation has been extensively studied in various solid tumors, such as breast cancer, ovarian cancer, prostate cancer, and pancreatic cancer." (PMID 38730642, 2024). "In patients with breast cancer, a high incidence of pathogenic variants of BRCA1 and BRCA2 is observed, as well as other highly mutated genes, such as PALB2, CHEK2, MUTYH, and ATM." (PMID 39335183, 2024).
breast cancer (continued). "Breast cells and breast cancer cells with germline BRCA1/2 mutations similarly show defects in liganded estrogen receptor (ER) signaling, demonstrating its role in genomic instability and cancer initiation." (PMID 39329990, 2024). "The location of PHB in the chromosome (17q21) is close to breast cancer susceptibility gene 1 (BRCA1) which links it to breast cancer easily." (PMID 37957856, 2024). "Ovarian cancer emerged as the most likely MPC among those with first primary breast cancer, supported by numerous studies and the established genetic link, especially in BRCA1/2 mutation carriers." (PMID 39001408, 2024). "Talazoparib group achieved higher curative effect with lower cost, that is, Talazoparib is more economical in treating advanced breast cancer patients with BRCA1/2 mutation." (PMID 38886516, 2024). "For the novel variants, protein structure modeling was conducted, and all deleterious variants were validated in another Finnish BRCA1/2-negative breast cancer population." (PMID 39272813, 2024). "In this subgroup, the cumulative risk of developing breast cancer up to the age of 80 years is about 72% in BRCA1 and 69% in BRCA2 pathogenic variant carriers." (PMID 38892081, 2024). "Having a BRCA1 mutation significantly elevates a woman’s chances of experiencing breast cancer throughout her lifetime, with a risk as high as 85%, and increases the likelihood of ovarian cancer to approximately 40–50%." (PMID 39594243, 2024). "Despite our observations of poorer outcomes in patients with PTEN-altered tumors, a 61-year-old breast cancer patient treated in cohort 1 with co-occurring deleterious BRCA1 and PTEN mutations experienced a prolonged PR." (PMID 39085400, 2024). "In order to pick the most effective treatment for initial chemotherapy, it is crucial to identify breast cancer patients who have a BRCA1/2 mutation." (PMID 39449897, 2024). "This study aimed to investigate the contralateral breast cancer (CBC) recurrence rate in Korean breast cancer patients according to their BRCA1/2 germline mutation status, focusing particularly on the CBC recurrence risk in BRCA1/2 negative (BRCAx) patients." (PMID 38254240, 2024). "For the example of female breast cancer, individuals in the top 0.3% of the breast cancer Enhanced PRS distribution have an equivalent average lifetime risk to deleterious mutation carriers for BRCA1 or BRCA2 genes in UK Biobank (35% to age 70)." (PMID 39292644, 2024). "By contrast the risk for breast cancer for BRCA1/2 mutation carriers by 70–80 years of age is roughly five to seven times higher (55%–72% of women who inherit a harmful BRCA1 variant and 45%–69% of women who inherit a harmful BRCA2 variant)." (PMID 38717180, 2024). "Additional cancer cell lines were tested, including breast cancer cell lines with BRCA1 mutations (HCC1428 and HCC1937)." (PMID 38789724, 2024). "PALB2 is considered the third most significant breast cancer susceptibility gene after BRCA1/2 due to its penetrance and prevalence." (PMID 39684258, 2024). "In BRCA1 patients, there is a 40% risk of developing contralateral breast cancer at 20 years, but this can range from as high as 60% to as low as 38% if under 40 or over 50 years old at the time of the first breast cancer diagnosis." (PMID 38248108, 2024). "Despite the well-known benefits of PARP inhibitors for patients with BRCA1/2-associated breast cancer, resistance often occurs." (PMID 39334297, 2024). "In this study, from a US health care system perspective, adjuvant olaparib was a cost-effective option for patients with high-risk, early-stage breast cancer and a germline BRCA1/2 mutation." (PMID 38170520, 2024).
breast cancer (continued). "Bilateral mastectomy has been reported to reduce breast cancer risk by more than 90% in high-risk populations and BRCA1/2 mutation carriers, although the evidence regarding its survival benefits is lacking." (PMID 39590130, 2024). "This highlights the importance of considering both germline and somatic mutations in BRCA1/2 when evaluating breast cancer classification and treatment options." (PMID 39272660, 2024). "OlympiA, a phase III clinical trial, comprised 1836 early breast cancer patients carrying a pathogenic BRCA1/2 variant with TNBC or hormone receptor-positive HER2-negative breast cancer and compared 1 year of olaparib versus a placebo." (PMID 39201718, 2024). "This review aims to explore the current status and challenges associated with managing BRCA1/2-associated hereditary breast cancer in LMICs." (PMID 39421188, 2024). "The effect is more pronounced in the presence of PARP upregulation and homologous recombination (HR) deficiencies such as breast cancer-associated gene (BRCA1/2)." (PMID 38929955, 2024). "Women with a genetic predisposition, such as those with a germline mutation in the BRCA1/2 genes, have a significantly higher lifetime risk of developing breast cancer." (PMID 38817906, 2024). "BRCA1/2 are tumor-suppressor proteins participating in DNA damage repair pathways whose hereditary mutations are linked to the increased risk of breast cancer development." (PMID 38606093, 2024). "A recent study on a cohort of 411 Romanian patients diagnosed with breast cancer showed that the c.3607C>T, c.181T>G missense variants, the c.5266dupC, c.68_69delAG (p.GluValfs) frameshift variants are recurrent in BRCA1 carriers." (PMID 39272683, 2024). "A notable 5%–10% of newly diagnosed breast cancer cases are due to hereditary factors, mainly resulting from germline autosomal dominant mutations in the Breast Cancer Susceptibility Genes, BRCA1 and BRCA2." (PMID 39421188, 2024). "Currently, no studies exist regarding the influence of hormonal contraceptives on breast cancer risk in carriers of pV in breast and/or ovarian cancer genes other than BRCA1 and BRCA2." (PMID 39259360, 2024). "Both breast cancer patients and those with mutations in the BRCA1 tumor‐suppressor gene exhibit a decrease in cofilin expression." (PMID 39453820, 2024). "In conclusion, BRCA1/2-mutated breast cancers were likely to be HER2- (P < 0.001) and Ki67 ≥ 15% (P = 0.010)." (PMID 38167124, 2024). "BRCA1/2 mutations have been shown to impact not only breast cancer risk but also breast cancer outcomes." (PMID 38817906, 2024). "The other two young BRCA1/2 mutation patient underwent one ovarian induction cycle to preserve fertilization soon after breast cancer surgery and prior to chemotherapy." (PMID 38800375, 2024). "In our specific breast cancer context, it is well-established that germ-line mutations in the BRCA1 gene significantly elevate the risk of its development." (PMID 38786046, 2024). "For example, in BRCA1-deficient breast cancer mice, a model carrying the BRCA1C61G missence mutation were found to have broken the N-terminal RING domain of BRCA1, and be significantly resistant to PARPi." (PMID 39318358, 2024). "Among the thirteen BRCA1/2 mutation-carrying families, there were nine breast cancer families, two digestive tract cancer families, and two ovarian cancer families." (PMID 38167124, 2024). "Multiple studies, both retrospective and prospective, suggest that bilateral mastectomy reduces the risk of breast cancer by approximately 90% in BRCA1/2 carriers." (PMID 39421188, 2024). "Carboplatin yielded twice as many responses as docetaxel in individuals with germline BRCA1/2-mutated breast cancer." (PMID 39449897, 2024). "Breast cancer patients with BRCA1/2 pathogenic variants are at higher risk for contralateral breast cancer." (PMID 39507757, 2024). "Some pancreatic cancer is hereditary, and ~10% have germline mutations of Breast cancer 1/2 (BRCA1/2)." (PMID 37956396, 2024).
breast cancer (continued). "At age 21, when Kendra’s paternal aunt received her second breast cancer diagnosis, Kendra and her younger sister opted for genetic testing, revealing they both had pathogenic BRCA1 variants." (PMID 39050256, 2024). "Incidentally, for some women, having the opportunity to talk to other breast cancer survivors carrying a BRCA1/2 genetic mutation was a strong incentive to participate in this study's focus groups." (PMID 38192174, 2024). "Data analysis showed patient No4 had genetic mutation BRCA1 (breast cancer gene 1), and from anamnesis vitae breast cancer was reported in five generations by maternal side." (PMID 38685589, 2024). "The lifetime risk of breast cancer and ovarian cancer with BRCA1 mutation is approximately 60% (95% CI: 44–75%) and 59% (95% CI: 43–76%), respectively." (PMID 39125994, 2024). "On the other hand, in the serum of breast cancer patients with BRCA1 mutation, VEGF is significantly lower than in breast cancer patients without BRCA1 mutation." (PMID 38332226, 2024). "This method identified mutations in the BRCA1 gene with high sensitivity, offering a promising tool for genetic screening in breast cancer." (PMID 38730959, 2024). "**Breast cancer-specific risk factors: BRCA1/BRCA2 mutation status, early menarche, late menopause, high-density breast, first pregnancy after age 30, not breastfeeding, never having a full-term pregnancy." (PMID 38496074, 2024). "One the on hand, in the tumor tissue of breast cancer patients, BRCA1/2 mutation carrier showed a significant higher VEGF expression from patients without BRCA mutations." (PMID 38332226, 2024). "The tissue specificity of BRCA1 mutation-associated tumors suggested a potential relationship between BRCA1-loss and excessive estrogen signaling in breast cancer development." (PMID 38672654, 2024). "The BRCA1 gene is one of the greatest instances of a breast cancer susceptibility gene that is commonly repressed in sporadic breast tumours; yet, the CpG hypermethylation of BRCA1 has been linked to DNMT 3b overexpression." (PMID 39846533, 2024). "SPRED2 appears to activate autophagy by interacting with selective autophagic components, such as LC3, p62, a neighbor of breast cancer susceptibility gene I (BRCA1) and cathepsin D, as evidenced by co-immunoprecipitation of these molecules with SPRED2." (PMID 38892460, 2024). "While the biological subtype in the patients with pathogenic variants of BRCA2 resembles distribution of sporadic breast cancers to a great extent, most breast cancers in pathogenic BRCA1 variant carriers have TNBC subtype." (PMID 39319938, 2024). "While 75% of BRCA2-associated breast cancers are reported to be HR+, approximately 70% of BRCA1-associated breast cancers are TNBC20–23." (PMID 39060255, 2024). "The original BOADICEA model includes the following six risk factors: age, family history of breast cancer with age at diagnosis, family history of male breast cancer, family history of ovarian cancer, and genetic testing (BRCA1/2 and SNPs)." (PMID 39742377, 2024). "While it is well known that ~15% of TNBCs are associated with BRCA1 mutations, the frequency of gBRCAMUT is up to 8% of all hormone receptor-positive breast cancers, and about 40% of breast cancers with low hormone receptor expression." (PMID 39201718, 2024). "The lifetime risk of developing breast cancer for carriers of BRCA1 and BRCA2 is estimated at 57–65% and 45–49%, respectively." (PMID 39484212, 2024). "Prospective studies have shown that only 5–12% of all women younger than 40 years with a first breast cancer diagnosis were carriers of the BRCA1 or BRCA2 mutation." (PMID 38254240, 2024).